IL6 (interleukin 6)
Diseases named in the same sentence as IL6 in open-access papers (continued):
Sharing a sentence is not in itself a finding about the gene and the disease.
cancer (continued). "Our findings suggest that plasma levels of IL-6, IL-8, and IL-12p70 and the percentage of lymphocytes could predict the recurrence, metastasis, and progression of cancer." (PMID 36157224, 2022). "IL-6 is a pleiotropic cytokine that regulates the immune system and the inflammatory response and affects hematopoiesis, metabolism, organ development, and cancer growth." (PMID 36380355, 2022). "Therefore, viral oncogenes E6 and E7 would seem to stimulate chronic inflammation in the cancer microenvironment through IL-6 and IL-6R overexpression." (PMID 36010256, 2022). "For example, in malignant tumors, cancer-associated fibroblasts (CAFs) serve as the main source of inflammatory factors including CXCL12, CXCL1, and IL-6, and participate in the regulation of immune responses in various malignant tumors (e.g., pancreatic ductal adenocarcinoma)." (PMID 35967331, 2022). "Interestingly, TAMs are reported to regulate the activation of CAFs by releasing CXCL12 and IL-6, thereby forming a positive loop to endorse cancer progression." (PMID 36324128, 2022). "Cancer microenvironment cells stimulate monocytes and neutrophils to secrete, inter alia, interleukin 6 (IL-6), VEGF, and transforming growth factor β (TGF-β), causing general immunosuppression by inducing apoptosis of lymphocytes and a decrease in lymphopoiesis." (PMID 36713575, 2022). "Interestingly, few reports have demonstrated the role of IL-6 in enrichment of CSC population leading to cancer progression." (PMID 35300689, 2022). "Moreover, STAT3’s its abnormal activation together with altered IL-6 levels are often found in chronic inflammatory diseases as well as in the majority of patients suffering from cancer, making STAT3 and its pathway another attractive target in cancer therapy." (PMID 36185259, 2022). "Evidence of the dual role of IL‐6 indicates that these opposing systemic responses to acute and chronic exercise may both contribute to the inhibition of cancer progression." (PMID 35213038, 2022). "Indeed, excessive ROS formation and inflammatory cytokines release (i.e., tumoral necrosis factor-alpha [TNF-α], interleukin- 6, and 1β [IL-6 and IL-1β]) are master mediators of proteolytic systems and muscle atrophy during cancer." (PMID 35847939, 2022). "IL-6 is an activator of Stat3 and is elevated in a variety of cancers." (PMID 36080130, 2022). "A powerful example of SBT-100′s inhibitory and anti-inflammatory ability is also demonstrated by its ability to block the effect of IL-6 on cancer cells and normal cells in vitro by preventing STAT3 from transcribing target genes in the nucleus such as VEGF and PD-L1." (PMID 35886918, 2022). "Considering that IL6 and TNFα have a close interaction and play essential roles in inflammatory response and cancer long-term outcomes, the combination of them seems to be a potentially more accurate, predictive, and sensitive indicator for predicting cancer prognosis." (PMID 35859928, 2022). "Fibroblasts secrete IL-6 and IL-8 to maintain cancer stem cells." (PMID 36207295, 2022). "Macrophages affect the cancer population indirectly by producing cytokines like IL6, IL10, and IL2." (PMID 35294447, 2022). "Growing evidence suggests that IL-6 plays a role in cancer metastasis." (PMID 35159388, 2022). "Inhibiting HSC cell growth and inhibiting the IL-6/STAT3 pathway could be a promising technique for inhibiting cancer cell survival." (PMID 37829248, 2022). "IL-6 promotes tumorigenesis by regulating all hallmarks of cancer and multiple signaling pathways." (PMID 36471379, 2022). "Interleukin-6 (IL-6), which plays a role in chronic inflammation, is closely related to cancer." (PMID 35897788, 2022). "Moreover, IL-10 secreted by TAM regulates proliferation and invasion in gastric cancer cell STAT3 signaling, and IL-6 stimulation promotes the increased proliferation of cancer cells." (PMID 35799889, 2022).
cancer (continued). "Thus, the involvement of IL-6 in satellite cell-dependent myogenesis can promote skeletal muscle protein synthesis and hypertrophy and ameliorate cancer-related muscle wasting." (PMID 35454797, 2022). "The combination treatment-induced systemic immune response was evaluated by measuring the secretion of serum proinflammatory cytokines with ELISA assay, including tumor necrosis factor-alpha (TNF-α), interferon-gamma (IFN-γ) and interleukin-6 (IL-6), that play vital roles in anti-cancer immunity." (PMID 35812418, 2022). "Similarly, for λC being cancer proliferation rate promoted by anything other than adipocytes and IL6 (which have been directly included in the model)." (PMID 35294447, 2022). "The triggering of the CXCR4/CXCL12 signaling pathway enhances trans-endothelial migration and the homing and adhesion of cancer cells in the BM niche; it also increases the expression and excretion of other disease-progressing molecules (i.e., IL-6, integrins, and growth factors)." (PMID 35566637, 2022). "Increased expression of proinflammatory cytokines, such as IL6 and TNF, in the stress-associated cancer cell population suggests that these cells could have a substantial contribution to paracrine signaling." (PMID 35196078, 2022). "Currently available data suggests some innovative therapies aimed to reduce mortality in patients with STEMI and SARS-CoV-2 infection, including selective inhibitors of interleukin 1 or interleukin 6, especially in vulnerable patients, such as those with cancer." (PMID 36362770, 2022). "Additionally, IL-6-mediated activation of JAK2/STAT3 within cancer cells promotes the expression of PD-L1 and PD-L2 and checkpoint inhibition." (PMID 36700235, 2022). "For example, in vitro and in vivo studies have consistently showed that IGU could effectively protect against cancer-induced bone pain and bone destruction, probably via downregulating interleukin-6 production in a nuclear factor-κB-dependent manner." (PMID 35936067, 2022). "TAM-derived IL-6 contributes to cancer progression through IL-6/STAT3 pathway." (PMID 35672862, 2022). "Thus, the IL-6/JAK/STAT-3 pathway appears to regulate a majority of invasion-promoting functions in various cancer types, as well as in trophoblasts." (PMID 35625802, 2022). "Cancer cells can produce IL-6 (which stimulates the production of CRP) or, in some cases, CRP." (PMID 35385679, 2022). "In addition, cancer-associated fibroblasts with EMT-program were enriched in HG_M, participating in angiogenesis and immune regulation, such as IL6/STAT3 pathway activity." (PMID 35935940, 2022). "And then, IL-6 further promotes cancer cell invasion, lipid depletion and immunosuppression." (PMID 36185215, 2022). "Up-regulation of cytokines in the bone microenvironment may contribute to peripheral and central components of cancer-induced bone pain, as osteoclasts are derived from monocyte/macrophage hematopoietic lineage and express receptors for TNFα and IL-6." (PMID 35335997, 2022). "Specifically, IL-6 has been described as a prognostic factor in cancer." (PMID 36140470, 2022). "One of the immunostimulators, IL-6, was shown essential for the proliferation of cancer cells." (PMID 36551549, 2022). "Indeed, pre-clinical studies have demonstrated that STAT3 is activated in muscle mediated by IL-6 excess and significantly contributes to muscle wasting during cancer." (PMID 35847939, 2022). "A well-established gene regulatory network that links IL-6-mediated chronic inflammation with cancer consists of two distinct but complementary feedback loops, one involving IL-6, NF-kB, Lin28 and let-7 miRNA, and the other comprising IL-6, NF-kB, STAT3, miR-181b-1, miR-21, CYLD and PTEN." (PMID 35757000, 2022).
cancer (continued). "The biomarkers most significantly associated with short-term mortality were IL-6, IL-10, IL-8, MCP-1 (mainly inflammatory markers), FGF-21, ST1A1, 4E-BP1 and CST5 (classified by OLINK as cardiovascular markers) and FGF-23 (classified as a cancer marker)." (PMID 36209229, 2022). "Our results suggest that IL-6 or IL-8 inhibition might already be beneficial in early stages of cancer by preventing or slowing down metastasis." (PMID 35252204, 2022). "Given that, IL-6 is of particular interest in cancer research." (PMID 36429126, 2022). "In addition to intestinal microflora disorders, dysfunction of intestinal barrier driven by IL‐6 in cancer cachexia can exacerbate systemic inflammation and endotoxemia." (PMID 36105371, 2022). "The IL-6/STAT3 pathway is a classic signaling that can induce enhanced EMT process in cancers." (PMID 36304989, 2022). "IL-6 promotes cancer immune evasion and facilitates the development of HCC." (PMID 35223517, 2022). "Notably, accumulation of inflammatory mediators, such as transcription factors NFκB and STAT3 as well as cytokines IL-6 and TNF-α, has been linked to local and systemic immunosuppression associated with the progression of cancer." (PMID 35163219, 2022). "Interestingly, clinical data have shown that IL-6 was differentially expressed in the stromal portion of cancer tissues, while IL-6 upregulation was positively correlated with poor responsiveness to chemotherapy." (PMID 35326670, 2022). "Additionally, high levels of circulating IL-6 have been reported to be positively correlated with cancer metastasis." (PMID 35361764, 2022). "These imply that controlling adipocytes and IL6 (in that order) might be a gateway to controlling cancer proliferation in these mice." (PMID 35294447, 2022). "Since TC is more intense close to the boundary and IL6 and A have the same behavior as in the previous case, one might expect to see fewer cancer cells at the boundary." (PMID 35629230, 2022). "Cancer cells, as well as inflammatory and stromal cells, can produce IL-6." (PMID 35884907, 2022). "STAT3 activation by IL-6 has been shown to regulate MSC-induced chemoresistance, and the blockage of STAT3 activation (with AG490, a JAK2 inhibitor) improved the susceptibility of cancer cells to chemotherapeutic agents." (PMID 35954425, 2022). "In addition, an independent study demonstrated that in lung cancer, CAFs promote epithelial-to-mesenchymal transition and enhance the metastatic potential of cancer cells through an IL-6 mediated pathway." (PMID 35186923, 2022). "IL-6 blocked apoptosis during inflammation, which could also protect cancer cells from apoptosis and chemotherapeutic agents." (PMID 36313710, 2022). "Interleukin-6 (IL-6) is a cytokine involved in many biological processes, playing an important role in the development of several illnesses such as inflammatory ones like cancer, in which its levels are increased." (PMID 35590912, 2022). "The studies were found that DRD2 was upregulated in many cancers and could increase IL-6 production." (PMID 35280511, 2022). "It was reported that treatment of patients with cancer with PD-1 immune checkpoint inhibitor could induce the production of IL-6." (PMID 34875483, 2022). "Several studies have explored the PD-L1 expression mediated by IL-6 in certain cancer types." (PMID 36362062, 2022). "In contrast, postoperative complications aggravate the prognosis of patients with malignancy, increase the levels of inflammatory cytokines, such as interleukin-6 (IL-6), and may lead to the proliferation of residual cancer cells." (PMID 35875086, 2022). "Additionally, cancer cells treated with recombinant IL-6 also showed increased CSCs expression which was abrogated upon pre-treatment with Stattic." (PMID 35300689, 2022). "Some cytokines, including IL-1 and IL-6, are released during cancer progression." (PMID 35915403, 2022).
cancer (continued). "Additionally, the use of fucoidan (400 mL/day) has also been used as an anti-inflammatory agent in cancer patients where it demonstrated a reduction in cytokines including IL-6, TNF-a and IL-1β after its oral administration." (PMID 36501043, 2022). "In addition, IL-6/JAK/STAT3 pathway inhibition has a synergistic antitumor effect with conventional cancer treatments, e.g., its effect is enhanced in combination with chemotherapy and radiotherapy." (PMID 35089951, 2022). "Hence, once removed from cancer cells, IL6, IL8, VEGF, CDKN2A and LMNB1 mRNA levels in MSCs return to levels observed in MSCs without cancer cells." (PMID 36358839, 2022). "Inhibiting the IL-6/STAT3 signaling pathway has become a therapeutic option for cancer progression." (PMID 37829248, 2022). "Moreover, activated IL-6-OPN signaling during fibroblast–cancer cell interaction enhances cancer cell growth, migration, and invasion." (PMID 35903297, 2022). "IL-6 is primarily expressed by CAFs and promotes cancer stemness." (PMID 35740372, 2022). "Consistently, IL-6/STAT3 signaling in cancerous EMT also results in the acquisition of cancer stemness in cancer cells; the self-renewal and population expansion of CSCs requires STAT3 in cooperation with stem-cell-associated transcription factors, such as NANOG." (PMID 36010693, 2022). "The cytokine interleukin 6 (IL-6) is involved in the pathogenesis of different inflammatory diseases, including cancer, and its monitoring could help diagnosis, prognosis of relapse-free survival and recurrence." (PMID 35676309, 2022). "Type 1 cytokine-like interleukins (IL-6, IL-8, and IL-18) present in blood plasma may indicate the presence of various diseases, including cancer." (PMID 35563131, 2022). "Increased IL-6 serum levels seem to be closely associated with cancer patients' clinical condition and to correlate with survival independent of the cancer type." (PMID 35872912, 2022). "Also, IL-6 through PGK1 phosphorylation in cancer cells and lncRNAs released from TAM increases tumor cell glycolysis and thereby boosts malignant progression." (PMID 36072596, 2022). "Appropriate expression of IL-6 is of great importance for human immune defence, but its sustained production has a pivotal role in the occurrence of multiple inflammation-related diseases and cancer." (PMID 36163033, 2022). "G-CSF and IL-6 produced by tumor cells in circulating conditions also induced the accumulation of neutrophils in pre-metastatic organs to facilitate the colonization of disseminated cancer cells." (PMID 35267547, 2022). "Additionally, IL-6 can promote cancer progression in a paracrine way by affecting the IL-6 receptor." (PMID 36232388, 2022). "Thus, IL-6-initiated signalling gains higher complexity and involves multifaceted mechanisms of action crucial for shaping the course of cancer progression." (PMID 36429126, 2022). "Moreover, the invasion and metastasis of cancer cells is promoted by hypoxia because it can induce the expression of interleukin (IL)-6, platelet-derived growth factor (PDGF) and transforming growth factor (TGF)-β." (PMID 35283421, 2022). "Furthermore, a retrospective clinical study involving 144 hospitalized patients with cancers showed that simultaneously elevated IL6 and TNFα levels had a nearly 6-fold increase in mortality." (PMID 35859928, 2022). "Some of the significant cancer hallmark terms are epithelial-mesenchymal transition (MSX1, CXCL12, SCG2, SLIT2), KRAS signaling up (F13A1, ADAMDEC1), inflammatory response (CCL5, VIP), IL-6/JAK/STAT3 signaling (CXCL13)." (PMID 35486660, 2022). "IL-6 is an inflammatory molecule which is produced and secreted by various cell types that confer an aggressive behavior and poor response to therapies in many cancers as well as CCA." (PMID 36091805, 2022). "It has been reported that IL-6 could induce mitochondrial dysfunction in adipocytes and regulate skeletal muscle mitochondrial remodeling in cancer cachexia." (PMID 35528525, 2022).
cancer (continued). "Numerous in vitro studies examining cell types, such as IGROV-1, PEO1, SKOV3, and OVCAR3, have reported that tumor necrosis factor-alpha (TNF-α), IL-6, and IL-8 act as potent paracrine and autocrine signaling molecules that regulate cancer cell invasion, proliferation, and bulk tumor growth." (PMID 35326569, 2022). "In particular, urokinase plasminogen activator (uPA) and urokinase plasminogen activator receptor (uPAR) are shown to be involved in the migration of NSCs to malignant tumors, as well as various cytokines including interleukin-6 (IL-6), interleukin-8 (IL-8), and monocyte chemoattractant protein-1." (PMID 35240798, 2022). "Oncogenic RAS-induced secretion of IL-6 can link chronic inflammation and cancer." (PMID 36313280, 2022). "Thus, the IL-6/STAT3 pathway appears to play a more complex role than just promoting cancer growth, even though several studies show a good correlation between activation of this pathway in epithelial cells and cancer progression." (PMID 35757757, 2022). "As mentioned in the previous section, adipocytes and IL6 play a big role in cancer dynamics." (PMID 35294447, 2022). "IL-6 and RasGRP1 have been shown to have important functions during inflammation and cancer." (PMID 36385095, 2022). "This is because the macrophages secrete IL-6, and then IL-6 helps promote cancer." (PMID 36294824, 2022). "STAT3 is also a downstream cellular mediator of cancer and angiogenesis, induced by IL-6 and EGFR." (PMID 36145523, 2022). "IL6 is an M2 macrophage-secreted cytokine that facilitates metastatic activity in cancer cells." (PMID 35455650, 2022). "STAT3 activation can induce cancer-promoting inflammation mediated by nuclear factor-kappa B (NF-κB) and IL-6/GP130/JAK pathways while suppressing NF-κB- and STAT1-mediated Th1 antitumor immune responses by decreasing the expression of antitumor cytokines such as IL-12 and IFN." (PMID 36557902, 2022). "The most important explanatory variables for pulmonary abnormalities by three unrelated classifiers (C5.0, RF, and glmNet) included preexisting malignancy, multimorbidity, markers of systemic inflammation (IL-6 and CRP), and anti-S1/S2 antibody levels at the 60-day follow-up." (PMID 35131031, 2022). "In addition, MSCs supported drug resistance through STAT-3 signaling in cancer cells activated by IL-6." (PMID 35582537, 2022). "Furthermore, the activation of NF-κB by IL-6 was sufficient to induce an epigenetic switch from breast immortalized cells to cancer stem cells in a single event of dedifferentiation." (PMID 35806442, 2022). "Third, growth factors and cytokines such as TNF-α, vascular endothelial growth factor and IL-6 induced by the inflammatory response could promote the proliferation and metastasis of residual cancer cells." (PMID 35194147, 2022). "For example, IL-1β and IL-6 have also been reported as key players in development of cancer." (PMID 35911555, 2022). "The systemic effect of IL-6 leads to the wasting of cancer patients." (PMID 35055153, 2022). "IL-6 can activate AP-1 and STAT3 TFs; both factors are implicated with dual behaviors in cancer." (PMID 36544764, 2022). "We found similarities in pathways and upstream regulators of FOXO3-deficient macrophages with HFD obese mice colon associated with inflammation (IL-1A, IL-1B, IL-6, IL-8 signaling), growth (ILK signaling, CDK5 signaling, VEGF signaling) and cancer (cAMP-mediated signaling)." (PMID 35323693, 2022). "Eight cytokines (IL-1β, IL-6, IL-10, TGF-β, CCL2, CXCL8, CSF-1, and VEGF) were identified to have higher expression values in the high-risk group than in the low-risk group, which was relevant to the progression, invasion, and metastasis of cancers." (PMID 36120553, 2022). "IL-6 plays an imperative role in the stemness enrichment of cancer cells." (PMID 36550571, 2022). "Apart from cancer cells, CAFs can also utilize secretory autophagy to manipulate IL-6 secretion." (PMID 35927755, 2022).